MTOR (mechanistic target of rapamycin kinase)
Diseases named in the same sentence as MTOR in open-access papers (continued):
Sharing a sentence is not in itself a finding about the gene and the disease.
breast cancer (continued). "Furthermore, the role of miR-544a was tested also in a hypoxic breast cancer model because it was able to silence the mammalian target of rapamycin (mTOR)." (PMID 27275761, 2016). "Thus, combined IGF-1R/mTOR inhibition plus hormone therapy in breast cancer cells presents as a viable therapeutic option." (PMID 27765027, 2016). "This hypothesis is substantiated by the relatively strong correlation between the decreased total mTOR protein induced by metformin and the resultant inhibition of proliferation and migration of breast cancer cells." (PMID 27748082, 2016). "In the case of mTOR (mammalian target of rapamycin) inhibitor, everolimus is approved for the treatment of neuroendocrine tumor and renal cell carcinoma (as single-agent), and breast cancer (in combination with hormonal therapy)." (PMID 26563120, 2016). "Our findings suggest that CAF proteins may be potential biomarkers in breast cancer for response to mTOR inhibition, and further studies may be performed to evaluate this." (PMID 27487140, 2016). "Since over-activation of the PI3K-Akt-mTOR pathway has been reported to be associated with cellular proliferation and patient prognosis, we investigated the clinical implications of high and low DRS in breast cancer patients." (PMID 27589846, 2016). "Therefore, targeting mTOR appears to be an important mechanism by which miR-100 sensitizes breast cancer cells to paclitaxel." (PMID 26744318, 2016). "It has been previously suggested that resistance to PI3K inhibition in breast carcinoma may lead to therapy resistance in part by activation of the mTOR pathway." (PMID 27120806, 2016). "We have addressed the question of whether mTOR inhibitors may be more effective in combination than singly in inhibiting the proliferation of breast cancer cells." (PMID 26148118, 2015). "We propose a randomized clinical trial to test whether the 31-gene AKT module could be used to identify estrogen receptor positive breast cancer patients who may benefit from therapy targeting the PI3K/AKT/mTOR signaling axis." (PMID 25886003, 2015). "Everolimus is an oral mTOR inhibitor which has been approved for use in post-menopausal women with HR-positive breast cancer; it is also approved for used in other cancers including renal cell carcinoma, neuroendocrine tumors of the pancreas and subependymal giant cell astrocytomas." (PMID 26779371, 2015). "A recent report showed that the type II IL4R was expressed and activated in human breast cancer and the metastatic capacity was decreased by knocking down IL4Rα, therefore inactivating Erk1/2, Akt and mTor induced reduction in breast cancer proliferation and survival." (PMID 26313265, 2015). "Combination mTOR/MEK inhibitor treatment resulted in decreased tumor size in MCF-7 human breast cancer xenografts, decreased androgen-dependent prostate cancer cell growth in vitro, and decreased androgen-independent prostate cancer cell growth in vitro and in vivo." (PMID 26121028, 2015). "Hence, type 2 diabetes mellitus can further accelerate the growth of HER2-positive breast cancer given that AKT/mTOR signaling is already active." (PMID 25935404, 2015). "They concluded that BN107 and OA are strong inhibitors of the Akt/mammalian target of rapamycin (mTOR) pathway, which could avoid chemoresistance development in ER− breast cancer cells." (PMID 26225949, 2015). "Thus, mTOR is an attractive, clinically relevant molecular target for drugs designed to treat metastatic breast cancers." (PMID 26132202, 2015). "Moreover, AMPK activation induced by AMPK activator negatively regulates the glycolysis-dependent metabolism in tamoxifen-resistant breast cancer cells by inhibiting mTOR/HIF-1α signaling." (PMID 26158266, 2015). "Finally, in breast cancer cells, it depleted cyclin E, inhibited the mammalian target of rapamycin (mTOR) pathway, and induced autophagy." (PMID 26313261, 2015).
breast cancer (continued). "Because mTOR inactivation was observed in breast cancer cells treated with phenformin, it was reasonable to investigate whether phenformin regulated EMT." (PMID 26114294, 2015). "Thus, simultaneous inhibition of Hhat and PI3K/mTOR signaling effectively reduces breast cancer cell proliferation." (PMID 25889650, 2015). "We conclude that tumor level and localization of pS6 are associated with therapeutic response in breast cancer and represent biomarkers to distinguish which tumors will benefit from the incorporation of PI3K/Akt/mTOR inhibitors with neoadjuvant endocrine therapy." (PMID 26098779, 2015). "The results suggest that judicious combination of mTOR inhibitors with different modes of action could have beneficial effects in the treatment of breast cancer." (PMID 26148118, 2015). "MicroRNA 99a overexpression has been shown to induce G1 cell-cycle arrest and apoptosis by lowering expression of the mammalian target of rapamycin (mTOR) gene, with miR-99a being a potential candidate for use as a therapeutic strategy for effectively controlling breast cancer development." (PMID 26220712, 2015). "Finally, inhibition of the Akt/mTOR pathway resulted in less accumulation of lactate in the LCC2 cells and glycolysis inhibition induced repression of Akt/mTOR/HIF-1α axis in tamoxifen-resistant breast cancer cell-specific manner." (PMID 26158266, 2015). "Since several AKT/mTOR pathway inhibitors have been shown to be effective for endocrine-resistant breast cancer cell lines, we decided next to investigate if the in vivo derived AKT gene module would be able to predict the response to drugs targeting the AKT/mTOR pathway." (PMID 25886003, 2015). "Interestingly, in several human normal and neoplastic cell lines, including MDA-MB-468 breast cancer cells, impairment of mTOR pathway by rapamycin was found to inhibit cell motility or invasion." (PMID 25880005, 2015). "The inhibitor of mTOR was shown to restore breast cancer cells’ sensitivity to hormone." (PMID 26558177, 2015). "Mammalian target of rapamycin (mTOR) is activated by insulin and insulin-mediated breast cancer progression in patients with type 2 diabetes mellitus may be abrogated by inhibition of mTOR." (PMID 26537234, 2015). "The importance of the PI3K/Akt/mTor signaling pathway in HER2-amplified breast cancers has been known for some time, and the idea of combining inhibitors of HER2 with inhibitors of this downstream pathway has been studied and showed superior activity in a number of preclinical studies." (PMID 26516700, 2015). "Importantly, breast cancer cell lines with high activity of the module respond preferentially to PI3K/AKT/mTOR inhibitors, a result we also validate in two independent datasets." (PMID 25886003, 2015). "PI3K, AKT and mTOR inhibitors are used clinically for the treatment of breast cancer." (PMID 25857298, 2015). "Indeed, a recent report suggests that PKD3 can directly phosphorylate and activate S6K1, in an mTOR-independent manner, which contributes to breast cancer cell growth." (PMID 25798941, 2015). "The most importantly, this is the first report to demonstrate that alterations in glucose metabolism are revealed in tamoxifen-resistant breast cancer cells and that the HIF-1α pathway and Akt/mTOR oncogenic signaling molecules are associated with the Warburg effect in these cells." (PMID 26158266, 2015). "Additionally, the loss of phosphatase and tensin homolog (PTEN) activates the phosphatidylinositide 3-kinase/Akt (PI3K/Akt) and mammalian target of rapamycin (mTOR) pathways, which leads to upregulation of PD-L1 on glioma and breast cancer cells." (PMID 25889536, 2015).
breast cancer (continued). "Recently, the PI3K/AKT/mTOR signaling pathway, which transmits signals from cell membrane into nucleus and activates multiple oncogenic programs, has been reported to play an important role in the regulation of autophagy in breast cancer cells." (PMID 26666173, 2015). "Moreover, the PI3K/Akt/mTOR pathway has been described as potentially intervening in secondary endocrine resistance in ER+ breast cancer." (PMID 26059247, 2015). "Collectively, these results demonstrate that inhibition of mTOR activity significantly potentiates etoposide-mediated cell death in breast cancer, suggesting that breast cancer cells may rely on the mTORC2-Chk1 pathway for survival." (PMID 25460505, 2015). "A similar mechanism has also been proposed in the study of an mTOR inhibitor on breast cancer." (PMID 25909285, 2015). "In conclusion, our study sheds further light on downstream mTOR signalling in breast cancer, supporting that S6K1 and S6K2 signalling may in part possess different roles in tumourigenesis." (PMID 26698305, 2015). "Everolimus, a small molecule inhibitor of mammalian target of rapamycin (mTOR) and recombinant human endostatin are other anti-angiogenic molecules that undergo clinical trials and might be used in treatment settings of breast cancer." (PMID 26006245, 2015). "Our results provide the rationale to design in vivo studies in the future, which may represent a novel strategy to enhance the efficacy of mTOR-targeted breast cancer therapy." (PMID 26148118, 2015). "Moreover preclinical evidence shows that inhibitors of PI3K or mTOR can restore sensitivity in breast cancer, non-small-cell lung cancer and glioblastoma cells resistant to biologic and cytotoxic drugs." (PMID 26097872, 2015). "Since metformin inhibits the mTOR/p3K pathway, it seems attractive to test this drug in tumours which harbour mTOR hyperactivation, such as neuroendocrine tumours (to be initiated by our group) and breast cancer (NCT01101438)." (PMID 26316884, 2015). "Dysregulation of mTOR signaling pathway, which is due to genetic variation of several key genes, has bene observed in different types of cancers, such as urothelial bladder cancer, breast cancer, hepatocellular carcinoma and lung cancer." (PMID 25680114, 2015). "Similarly, we compared basal autophagy response by inducing autophagy with the mTOR inhibitor RAD001 under full medium (FM) conditions in breast cancer MCF7 cells and human pancreatic duct epithelial (HPDE) cells." (PMID 26253153, 2015). "Indeed preclinical data support the suggestion that targeting of the PI3k/mTOR pathway in combination with trastuzumab is beneficial in trastuzumab-resistant breast cancer." (PMID 25678856, 2015). "PIK3CA mutation may contribute to the poor outcome of ER positive breast carcinomas, providing evidence for the combination of PI3K/AKT/mTOR inhibitors and endocrine therapy." (PMID 25816324, 2015). "Results in this study demonstrate that LIF activates the mTOR pathway in breast cancer." (PMID 24553191, 2014). "In breast cancer, numerous cell signaling pathways are aberrantly activated to produce the myriad phenotypes associated with malignancy; such pathways include the PI3K/Akt/mTOR, NF-κB and JAK/STAT cascades." (PMID 25153725, 2014). "A recent study showed that patients with gynecologic and breast cancer that have PIK3CA mutations are more responsive to treatment with PI3K/AKT/mTOR inhibitors than patients without mutations." (PMID 25344912, 2014). "The activation of mTOR and the subsequent phosphorylation and activation of its downstream targets p70S6K and eIF4E binding protein 1 (4EBP1) play an important role in promoting cell growth, proliferation and metastasis in breast cancers." (PMID 24553191, 2014).
breast cancer (continued). "Additionally a synergistic relationship exists between treatment of ER+ breast cancers with endocrine therapies and mTOR inhibitors in breast cancer cell lines." (PMID 25283550, 2014). "Future studies will also investigate whether the miR-99a-mediated inhibition of mTOR signaling pathway could be used as a potential therapeutic strategy to effectively control breast cancer in clinic." (PMID 24637915, 2014). "Aberrant gene expression of mTOR pathway alters cell growth and apoptosis in many cancer types such as prostate cancer, lung cancer, acute myelogenous leukemia, hepatocellular carcinoma, gastric cancer and breast cancer." (PMID 24637915, 2014). "The observed correlation between a direct marker of mTOR activation, p-S2448 mTOR, and the P7-ERα score in ERα + primary breast cancer cases prompted us to investigate the ability of estrogen to regulate phosphorylation of mTOR in MCF7 human breast cancer cells." (PMID 24887419, 2014). "mTOR plays a critical role in mediating miR-99a dependent biological functions in breast cancer." (PMID 24637915, 2014). "Furthermore, the inhibition of breast cancer cell viability and the acceleration of apoptosis by miR-99a mimics were rescued by restoration of mTOR expression." (PMID 24637915, 2014). "Given the clinical context of these mutations in breast cancer, these mutations are of potential clinical benefit to the patient that may have implications for PIK3CA inhibitors that target the PI3K/AKT/mTOR pathway." (PMID 24885028, 2014). "The AKT/mammalian target of rapamycin (mTOR) signaling pathway is regulated by 17α-estradiol (E2) signaling and mediates E2-induced proliferation and progesterone receptor (PgR) expression in breast cancer." (PMID 25283550, 2014). "To further test whether miR-99a-mediated mTOR inhibition confers antitumor activity in breast cancer cells, we first confirmed the biological functions of miR-99a mimics-transfected breast cancer by inhibiting mTOR expression." (PMID 24637915, 2014). "mTOR expression was similar in all four breast cancer cell lines." (PMID 24866893, 2014). "To further determine whether miR-99a inhibits mTOR expression in human breast cancer cells, we transfected miR-99a mimics into MCF-7 cells and analyzed mRNA and protein levels by qRT-PCR and immunoblot." (PMID 24637915, 2014). "This suggested that FASN expression was more closely associated with HER2 expression than with ER expression in breast cancer cells, whereas mTOR expression was independent of HER2 and ER status." (PMID 24866893, 2014). "Thus, the current study provides a strong support of miR-99-targeted mTOR/p-4E-BP1/p-S6K1 signaling pathway in breast cancer cells." (PMID 24637915, 2014). "As NEDD4 negatively regulates PTEN stability, NEDD4 could possibly promote cell growth and migration partly through activation of the mTOR/Akt pathway in prostate and breast cancers." (PMID 24657926, 2014). "We found that LIF activates the mTOR pathway in breast cancer cells." (PMID 24553191, 2014). "Interestingly, targeting the PI3K/AKT/mTOR pathway is one of the most-promising therapeutic approaches to reversing endocrine resistance for ER positive breast cancer." (PMID 24416132, 2014). "When analyzing the results by tumor type, alterations of the PI3K/AKT/mTOR pathway in breast cancer were not linked with worse outcome." (PMID 24777052, 2014). "Future studies could take into consideration the role hyperactive mTOR and metabolism play in metastatic disease, and how best to treat this more lethal form of breast cancer and whether cell autonomous mechanisms are involved." (PMID 25436981, 2014). "Loss of PTEN, a negative regulator of the PI3K/AKT/mTOR pathway, frequently occurs in breast cancer, but did not have clinical validity as a single marker in a previous study." (PMID 24467828, 2014).
breast cancer (continued). "Similar strategies for targeting a signaling pathway from multiple directions have proven effective in other cancers, as one study highlights that mTORC and HDAC inhibition mechanistically converged on the PI3K/AKT/mTOR pathway to reduce breast cancer cell viability." (PMID 25347326, 2014). "The decrease of p-mTOR was also found to be significant in HER2-positive patients compared with HER2-negative patients, indicating that the PI3K/Akt/mTOR pathway may be suppressed more effectively by chemotherapy in HER2-positive breast cancers." (PMID 25364442, 2014). "Thus, enhanced Akt/PI3K/mTOR activation represents an interesting target for treating ER+ breast cancer." (PMID 25338520, 2014). "Acquisition of resistance to endocrine therapy remains a major problem in the treatment of ER + breast cancer and using inhibitors to target de-regulated growth factor signalling pathways, such as mTOR, has become an important therapeutic approach currently under intense clinical evaluation." (PMID 24457069, 2014). "We further showed the mTOR pathway to be important in regulating OXPHOS in breast cancer cells and found that manipulation of expression of the key molecules such as p70S6K could significantly alter mitochondrial respiration and glucose metabolism." (PMID 25209360, 2014). "Besides, cell survival maintained by Aur-A overexpression in response to nutrient deprivation was restrained by suppression of mTOR activity, indicating a critical role of mTOR for the aberrant Aur-A signaling in breast cancer cells." (PMID 25115395, 2014). "Furthermore, miR-99a expression was statistically inversely correlated with mTOR expression in both breast cancer tissue specimens and cell lines." (PMID 24637915, 2014). "Thus, our study investigated the biological functions and mechanisms of miR-99a as antitumor miRNA by repressing the activity of mTOR in breast cancer cells in vitro as well as in nude mouse xenografts." (PMID 24637915, 2014). "Our results have established that mTOR was a direct target of miR-99a in breast cancer cells." (PMID 24637915, 2014). "Increased mTOR activity was suggested as a mechanism of resistance to IGF-1R inhibition in Ewing's Sarcoma as well as in a case of acquired resistance to HER2 receptor inhibitor lapatinib in breast cancer." (PMID 25344862, 2014). "Our results point to the existence of sub-lines of the MCF-7 breast cancer cell line where resistance to 4-hydroxytamoxifen is coupled to increased resistance to inhibitors of the mTOR pathway but increased sensitivity to a variety of cytotoxic anticancer drugs." (PMID 25232533, 2014). "In this study, we have evaluated the relationship between activated mTOR signaling and the ERα phosphorylation score, as a measure of the balance of ligand-dependent and -independent ERα signaling, using human breast cancer cases, where the patient subsequently received adjuvant tamoxifen therapy." (PMID 24887419, 2014). "Indeed, preclinical studies have shown that the mTOR antagonists can restore endocrine sensitivity in breast cancer cells." (PMID 23389114, 2013). "In human breast cancer, the prognostic significance of p-mTOR expression is still controversial." (PMID 23587222, 2013). "Taken together, our results indicate that anthricin is an inhibitor of mTOR and that a combination of an autophagy inhibitor and anthricin may serve as a new promising strategy for the treatment of breast cancer cells." (PMID 23818925, 2013). "In addition to HCC, the inhibitory effect of matrine on the PI3K/AKT/mTOR pathway has also been reported in gastric cancer, acute myeloid leukemia, breast cancer, and other malignancies." (PMID 24287900, 2013). "In this study, we documented enhanced activation of PI3K/Akt/mTOR in BCSCs of primary human breast cancer and two xenografts of primary tumors, and suppressive effects of the mTOR inhibitor, rapamycin, on their growth in vitro and in vivo, as well as mammosphere formation." (PMID 23663564, 2013).